HMGA2 (high mobility group AT-hook 2)
Diseases named in the same sentence as HMGA2 in open-access papers (continued):
Sharing a sentence is not in itself a finding about the gene and the disease.
cryptorchidism (3 papers, 2020 to 2022). The failure of one or both testes of a male fetus to descend from the abdomen into the scrotum during the late part of pregnancy. "In pig, targeted HMGA2 null males exhibited impaired fertility with evidence of impaired spermatogenesis, and cryptorchidism." (PMID 34878116, 2022). "In particular, Hmga2−/− pigs show cryptorchidism, and hence the sterility is possibly due to absence of spermatogenetic cells caused by undescended testes; whereas, transgenic Hmga2−/− mice have normally descended testes but no mature sperms because of impaired spermatogenesis." (PMID 31963852, 2020).
endometrial tumor (3 papers, 2016 to 2019). "To determine the function of HMGA2 and miR-302a-5p/367-3p in vivo, we analysed the effects of miR-302a-5p/367-3p overexpression or HMGA2 knockdown and their combinatorial effect on endometrial tumour xenografts in nude mice." (PMID 29391048, 2018). "We found increases in SLUG, ZEB1, and HMGA2 mRNA expression in the myoinvasive front of tumor samples, indicating the role of these transcriptional factors in endometrial tumor progression and invasion." (PMID 27429042, 2016).
esophageal adenocarcinoma (3 papers, 2014 to 2018). A malignant tumor with glandular differentiation arising predominantly from Barrett mucosa in the lower third of the esophagus. "Conversely, HMGA1, but not HMGA2, was overexpressed in esophageal adenocarcinoma samples." (PMID 27027341, 2016).
Ewing sarcoma (3 papers, 2021 to 2022). A small round cell tumor that lacks morphologic, immunohistochemical, and electron microscopic evidence of neuroectodermal differentiation. "HMGA2, IGF2BP2, IGF2BP3, and IGF2 were confirmed to be significantly overexpressed in CDS-derived cell lines compared with Ewing sarcoma–derived cell lines." (PMID 34903601, 2022). "qRT-PCR confirmed that CDS specimens exhibited significantly elevated expression of HMGA2, IGF2BP2, IGF2BP3, and IGF2, but not HMGA1, compared with Ewing sarcoma specimens." (PMID 34903601, 2022).
follicular adenomas (3 papers, 2014 to 2025). "The highest relative HMGA2 expression observed in 14 follicular adenomas was 17.4, whereas the expression levels in four FV PTC ranged between 23.9 and 156.9." (PMID 24516594, 2014). "HMGA2 was not present in normal tissues and in follicular adenoma, but was detected in the nucleus of most FTC." (PMID 29535811, 2018). "The strongest candidate genes which may be able to discriminate follicular adenomas and carcinomas, CRABP1, FABP4 and HMGA2, were validated in independent samples by qRT-PCR and immunohistochemistry." (PMID 29535811, 2018).
Insulin resistance (3 papers, 2020 to 2022). Increased resistance towards insulin, that is, diminished effectiveness of insulin in reducing blood glucose levels. "Furthermore, the Let-7 family is reported to target high-mobility group AT-hook 2 (HMGA2) and is considered involved in adipogenesis, glucose metabolism, insulin resistance, and inflammation." (PMID 33207733, 2020).
larynx carcinoma (3 papers, 2020 to 2022). A primary or metastatic malignant neoplasm involving the larynx. "Our study was designed to infer whether let-7a targets high-mobility AT-hook 2 (HMGA2) and suppresses laryngeal carcinoma cell proliferation, invasion, and migration." (PMID 32432318, 2020).
microcephaly (3 papers, 2023 to 2025). A congenital or acquired developmental disorder in which the circumference of the head is smaller than normal for the person's age and sex. "In patients with a mutation in the HMGA2 gene, microcephaly at birth has been described." (PMID 36947243, 2023). "However, microcephaly appears to be a highly penetrant and consistent feature in SRS-like patients harboring pathogenic variants in HMGA2." (PMID 38516887, 2024). "This has previously been reported for HMGA2 and PLAG1, only one IGF2 case had relative microcephaly." (PMID 41430624, 2025).
Myocardial fibrosis (3 papers, 2022 to 2025). "However, another study in a mouse model of myocardial remodeling demonstrates that the cardiac-specific expression of HMGA2 reduces myocardial fibrosis and improves cardiac function by activating the PPAR pathway." (PMID 36604692, 2023). "After 100 μg of MSC-EXO was administered to MI rats via the tail vein for 7 consecutive days, EZH2 expression was reduced, and high mobility group AT-hook 2 (HMGA2) expression was activated to block PI3K/AKT signaling, inhibiting myocardial fibrosis in MI rats." (PMID 41426560, 2025).
myoma (3 papers, 2016 to 2025). "Driver mutations in MED12, HMGA2 and other genes appear to be emerging in undifferentiated cells at the early stages of UL tumorigenesis and largely define the fate of each myoma." (PMID 36982825, 2023). "MED12 mutations could either be the only genetic aberration detected in a myoma or coexist with other “driver” mutations (HMGA2, FH, COL4A5-COL4A6)." (PMID 36982825, 2023). "There also seems to be a link between myoma formation and genetic aberrations, as cytogenetic tests showed abnormalities in 40% of the samples tested: 65% overexpressed the HMGA2 (high-mobility group AT-hook 2) gene." (PMID 40868086, 2025).
Neuroendocrine Tumors (3 papers, 2009 to 2020). "Neuroendocrine tumours of foregut showed the frequent HMGA2 overexpression and highest level of HMGA2 expression (P<0.05)." (PMID 19156147, 2009).
renal fibrosis (3 papers, 2019 to 2023). A final common manifestation of a wide variety of chronic kidney diseases characterized by glomerulosclerosis and tubulointerstitial fibrosis. "In vitro, using TGF-β1-induced NRK-52E cells, we found that miR-490-3p targeting HMGA2 was involved in renal fibrosis, and further showed that emodin via regulation of miR-490-3p/HMGA2 and ameliorates renal fibrosis." (PMID 36937888, 2023). "Another research reported that miR-98-5p mitigated renal fibrosis and epithelial-to-mesenchymal via modulating HMGA2 expression in DN." (PMID 34649592, 2021). "In our present study, it was revealed miR-98-5p was a significant modulator of EMT and renal fibrosis in DN via targeting HMGA2." (PMID 31885559, 2019). "Thus, as a novel target of emodin that prevents renal fibrosis in the HMGA2-dependent signaling pathway, miR-490-3p has potential implications in CKD pathology." (PMID 36937888, 2023). "Notably, TGF-β1 is a potent fibrogenic factor that can mediate EMT through the regulatory effects of HMGA2 and mediate the development of renal fibrosis through different signaling pathways." (PMID 36937888, 2023). "Overall, these revealed miR-98-5p could suppress the EMT process and renal fibrosis through targeting HMGA2 in DN." (PMID 31885559, 2019). "Thus, emodin may inhibit the HMGA2-dependent signaling pathway and reverse renal fibrosis by up-regulating miR-490-3p expression in NRK-52E cells." (PMID 36937888, 2023).
serous ovarian cancer (3 papers, 2018 to 2025). "Note that STC2 was found over-expressed and might be directly regulated by HMGA2 at the transcriptional level in high-grade serous ovarian cancer." (PMID 34475994, 2021).
synovial sarcoma (3 papers, 2017 to 2022). "HMGA2 is highly expressed in MPNSTs and can be used to distinguish this tumour type from synovial sarcomas, but the function of HMGA2 in MPNST growth and the underlying molecular mechanism have not yet been studied." (PMID 31053152, 2019). "For example, MDM2 amplification is present in most dedifferentiated liposarcomas and typically co-amplified with CDK4 and/or HMGA2, synovial sarcomas (SS) are often characterized by SS18–SSX fusions, and presence of MYOD1 mutations indicate spindle cell/sclerosing rhabdomyosarcoma." (PMID 35053600, 2022).
tongue cancer (3 papers, 2016 to 2021). A malignant neoplasm affecting the tongue. "An association of HMGA2 expression has been reported with locoregional and distant metastasis in tongue cancer." (PMID 33639654, 2021). "In addition, up-regulation of HMGA2 was closely associated with poor prognosis in tongue cancer patients." (PMID 26818837, 2016). "The results above demonstrate that overexpression of HMGA2 is associated with poorer survival in patients with tongue cancer; however, the mechanism and factors downstream of HMGA2 which mediate this effect are unknown." (PMID 26818837, 2016). "They further explored the effect of HMGA2 inhibition in tongue cancer cell lines and observed decreased invasiveness." (PMID 33639654, 2021). "HMGA2 has been associated with an aggressive cancer phenotype and induction of EMT by suppressing E-cadherin transcription in tongue cancer." (PMID 29507664, 2018). "As tongue cancer cells preferred to transfer to lymph nodes, we examined the expression of HMGA2 and Snail in the metastatic lymph nodes." (PMID 26818837, 2016). "In parallel with up-regulation of the HMGA2 protein, the five tongue cancer cell lines unexceptionally showed significantly higher levels of HMGA2 mRNA." (PMID 26818837, 2016). "Our data indicated that Snail is potentially involved in the EMT induction by interaction with HMGA2 in tongue cancer." (PMID 26818837, 2016). "All of these results indicate that HMGA2 was upregulated in tongue cancer cell lines and human tissues." (PMID 26818837, 2016). "Using the transwell chamber model, we observed that compared to untreated or vector transfecting tongue cancer cells, silencing of HMGA2 expression severely inhibited the migration and invasion ability of Cal27 and UM1cells." (PMID 26818837, 2016). "HMGA2 enhances tongue cancer metastasis and progression via interaction with Snail through EMT signal pathway." (PMID 26818837, 2016). "Taken together, our analyses revealed that the expression of HMGA2 was upregulated during the clinical progression of tongue cancer, indicating that the expression of HMGA2 may promote the progression of tongue cancer." (PMID 26818837, 2016). "In addition, knockdown of HMGA2 expression can severely impair tongue cancer cells migration, invasion and EMT process." (PMID 26818837, 2016). "The results demonstrated that HMGA2 protein was highly expressed in tongue cancer cell lines." (PMID 26818837, 2016). "In sum, overexpression of HMGA2 promotes tongue cancer cell migration and invasion in vitro." (PMID 26818837, 2016). "To determine whether the up-regulation of HMGA2 in tongue cancer cell lines is clinically correlated with tongue cancer progression, we did western blotting analysis on eight cases of paired primary matched adjacent non-neoplastic tongue tissue and tongue cancer samples." (PMID 26818837, 2016). "We found that both HMGA2 and Snail are highly expressed and co-localized in the nuclear of lymph nodes, indicating that there may be an interaction between HMGA2 and Snail, which may play an significant role in the metastasis process through EMT pathway activated by HMGA2 in tongue cancer." (PMID 26818837, 2016). "Collectively, these findings indicate that HMGA2 protein expression, but not Snail protein expression, correlates significantly with the prognosis of patients with tongue cancer." (PMID 26818837, 2016). "We show that the overexpression of HMGA2 can up-regulate Snail expression level and activate EMT, leading to poor clinical stage (P = 0.001), lymph node status (P = 0.000), poor histological differentiation (P = 0.002) and short survival (P = 0.000) in patients with tongue cancer." (PMID 26818837, 2016). "Additionally, using quantitative real-time PCR, 20 cases of paired primary matched adjacent non-neoplastic tongue tissue and tongue cancer samples were analyzed, most of cases had much higher HMGA2 expression levels, compared with adjacent non-neoplastic tongue tissues." (PMID 26818837, 2016).
adenocarcinomas of the breast (2 papers, 2020 to 2025). "Tumor entities with a particularly low expression of HMGA2 included prostatic adenocarcinomas (0.4–4%), non-invasive urothelial carcinomas (1.8–4.3%), adenocarcinomas of the breast (1.1–1.5%), and non-Hodgkin’s lymphomas (0%)." (PMID 40518465, 2025). "Breast adenocarcinoma cells overexpressing HMGA2 exhibit fewer apoptotic events compared to cells with low HMGA2 expression by a mechanism involving HMGA2-mediated inhibition of miR-34a and subsequent de-repression of Bcl-2." (PMID 32365712, 2020).
adipose tissue tumors (2 papers, 2009 to 2014). "They consistently showed high expression of HMGA2, arguing for the importance of deregulated HMGA2 expression also in this subtype of lipomatous tumors." (PMID 19508721, 2009). "This raises the interesting possibility that the level of cellular atypia may be influenced by the level of HMGA2 expression in lipomatous tumors with rings." (PMID 19508721, 2009). "Because of the apparent relationship of HMGA2 and PLAG1 in the molecular pathogenesis of salivary gland adenomas and adipose tissue tumors, we also quantified and compared the expression of HMGA2 and PLAG1 mRNA in thyroid adenomas as well as in papillary and follicular thyroid carcinomas." (PMID 24516594, 2014).
adrenocortical carcinoma (2 papers, 2019 to 2025). "Because 63% of 27 adrenocortical carcinomas were HMGA2 positive while all 47 adrenocortical adenomas were HMGA2 negative in our study, HMGA2 IHC may possibly serve as a marker of malignancy in adrenocortical neoplasms." (PMID 40518465, 2025).
B-cell chronic lymphocytic leukemia (2 papers, 2014 to 2023). "Additionally, EZH2 has actions that induce the PI3K/AKT pathway in clinically aggressive chronic lymphocytic leukemia, and it modulates the cardioprotective effects of mesenchymal-stem-cell-secreted exosomes via HMGA2-mediated PI3K/AKT signaling." (PMID 37445833, 2023).
benign connective tissue neoplasms (2 papers, 2015 to 2016). "High expression levels of HMGA2 have been found in various types of tumors including benign connective tissue neoplasms and malignant tumors." (PMID 27835588, 2016).
beta thalassaemia (2 papers, 2016 to 2025). "In a beta thalassaemia clinical trial, integration of a SIN LV resulted in 3’ end substitution of the HMGA2 gene that abolished let7 microRNA control of this protooncogene, reduced HMGA2 degradation and subsequent clonal proliferation." (PMID 40664913, 2025).
bladder urothelial carcinoma (2 papers, 2025). "This study investigated the presence and levels of the HMGA2 protein in bladder urothelial carcinoma patients’ plasma and in healthy individuals and their association with the clinicopathological features of bladder urothelial carcinoma." (PMID 40204943, 2025).
Brachycephaly (2 papers, 2021 to 2022). An abnormality of skull shape characterized by a decreased anterior-posterior diameter. "The altered craniofacial phenotype (brachycephaly) in HMGA2-null rabbits along with human GWAS indicating an association with craniofacial morphology, especially in the upper region of the face and nose, suggests that HMGA2 may have possible pleiotropic effects on craniofacial development." (PMID 34878116, 2022).
chronic pancreatitis (2 papers, 2003 to 2023). A chronic inflammatory process causing damage and fibrosis of the pancreatic parenchyma. "The signal intensities of the HMGA2 band in chronic pancreatitis tissue samples were almost equivalent to those observed in the normal tissue samples." (PMID 14647145, 2003). "Among the six non-neoplastic tissue samples, five, including three normal tissues and two chronic pancreatitis tissues, gave rise to detectable HMGA2 bands, while one normal tissue sample showed no detectable HMGA2 band." (PMID 14647145, 2003).
colorectal adenocarcinoma (2 papers, 2019 to 2025). The most common type of colorectal carcinoma. "HMGA2 is highly expressed in bronchial epithelial cells, colorectal adenocarcinoma, and smooth muscle." (PMID 31581665, 2019).
developmental delay (2 papers, 2015 to 2025). "Similar to previously published cases, one patient has haploinsufficiency of the HMGA2 gene and shows severe short stature and developmental delay." (PMID 26266063, 2015). "PLAG1, HMGA2, and IGF1R patients exhibited a lower frequency of body asymmetry and of relative macrocephaly at birth and postnatal life, while IGF2 patients displayed an increased frequency of feeding difficulties, heart defects, skeletal malformations, and developmental delay." (PMID 39412159, 2025).
embryonic rhabdomyosarcoma (2 papers, 2024 to 2025). "Also, HMGA2 can be an oncogenic driver in embryonic rhabdomyosarcoma through the HMGA2-IGFBP2-NRAS axis." (PMID 38802807, 2024). "In cancers such as embryonic rhabdomyosarcoma (ERMS), HMGA2 upregulates IMP2, stabilizing NRAS mRNA and sustaining oncogenic NRAS signaling." (PMID 40141058, 2025).
fibrosarcoma (2 papers, 2016 to 2019). A malignant mesenchymal fibroblastic neoplasm affecting the soft tissue and bone. "We detected PARylated HMGA2 in the PARylated protein fraction of MDA‐MB‐231 transfectants with stable expression of exogenous HMGA2 and in MDA‐MB‐436 and C1 fibrosarcoma cells (data not shown), both with endogenous HMGA2 expression, indicating that HMGA2 is PARylated upon PARP activation." (PMID 30289618, 2019).
follicular thyroid carcinoma (2 papers, 2014 to 2025). "Based on their HMGA2 expression, two groups of follicular thyroid carcinomas can be distinguished." (PMID 24516594, 2014). "Follicular carcinomas with high HMGA2 expression levels also express PLAG1 at elevated levels." (PMID 24516594, 2014). "In the subgroup of follicular carcinomas without or with only slight HMGA2 overexpression, the PLAG1 expression levels ranged between 0.3 and 0.6 in four cases while one case showed a slight overexpression (7.4)." (PMID 24516594, 2014).
glioma malignance (2 papers, 2018 to 2023). "The levels of the mRNA and protein of MMP2 were positively correlated with those of HMGA2, further confirming that HMGA2 overexpression promotes the cell invasion of malignant gliomas by directly activating MMP2 expression." (PMID 29733521, 2018). "In summary, we revealed previously unknown mechanisms of gliomagenesis and malignant progression driven by HMGA2 via direct activation of the transcription of the MMP2 gene, the HMGA2/GCN5 epigenetic regulation axis may provide novel targeting site in malignant glioma therapy." (PMID 29733521, 2018). "Our findings suggested that HMGA2 and MMP2 may be promising prognostic markers and potential therapy site in malignant gliomas." (PMID 29733521, 2018).
goiter (2 papers, 2019 to 2021). Enlargement of the thyroid gland usually caused by lack of iodine in the diet, hyperthyroidism, or thyroid nodules. "In comparison with other markers, the HMGA2 expression level was the best stand-alone marker for discrimination among goiters, benign tumors, and malignant tumors." (PMID 31660895, 2019). "In PTCs, the HMGA2 mRNA level was ~200-fold higher on average compared with that in goiters." (PMID 31660895, 2019). "Nevertheless, no overexpression of the selected miRNAs or HMGA2 was detected in any benign tumor or goiter with an elevated mtDNA/nDNA ratio." (PMID 31660895, 2019).
hamartoma (2 papers, 2024 to 2025). A benign and excessive tumor-like growth of mature cells and normal tissues which grow in a disorganized pattern. "It seems that hamartoma stromal cells expressed HMGA2, ER, and PR in 79%, 66%, and 76.3% of cases, respectively, compared to 7.7%, 23%, and 19% in normal breast tissue, respectively (p < 0.0001; p = 0.0005; p < 0.0001)." (PMID 40724578, 2025).
interstitial lung disease (2 papers, 2020 to 2021). A diverse group of lung diseases that affect the lung parenchyma. "Strikingly, FACTin treatment counteracted the effects observed in IPF hLF, supporting the involvement of the HMGA2-FACT-ATM-pH2A.X axis in this interstitial lung disease." (PMID 33594057, 2021). "The lack of HMGA2 expression in proliferating fibroblasts of some pulmonary interstitial diseases further suggests that the gene’s misexpression defines neoplastic transformation of a normal cell rather than a hyper-proliferative index." (PMID 32365712, 2020).